ALOX15 (arachidonate 15-lipoxygenase)
Diseases named in the same sentence as ALOX15 in open-access papers (continued):
Sharing a sentence is not in itself a finding about the gene and the disease.
Cerebral ischemia (4 papers, 2019 to 2024). Restriction of arterial blood supply to the brain associated with insufficient oxygenation to support the metabolic requirements of the tissue. "Using animal and cell models, Lei demonstrated that Alox15 is involved in ferroptosis and inflammation after cerebral ischemia–reperfusion injury." (PMID 40026597, 2024). "The Alox15 pathway, responsible for the metabolism of arachidonic acid, has been identified as a significant factor in cerebral ischemia injury." (PMID 40026597, 2024). "During cerebral ischemia–reperfusion injury, Alox15 may play a crucial role in regulating ferroptosis and inflammation." (PMID 40026597, 2024). "Moreover, it was reported to alleviate oxidation and inflammation after cerebral ischemia/reperfusion injury by reducing ALOX15 expression." (PMID 35186185, 2022). "Additionally, CEP was revealed to regulate the metabolism of AA by reducing the expression of COX-2 and ALOX15 in liver and brain ischemia/reperfusion models, respectively." (PMID 35186185, 2022).
chronic rhinosinusitis (4 papers, 2022 to 2025). Chronic form of sinusitis. "Because ALOX15 expression depends on IL-4 and IL-13, it has been suggested that dupilumab may counter type 2 inflammation in chronic rhinosinusitis in part by suppressing an IL-4/IL-13/ALOX15 M2 macrophage signaling axis." (PMID 38637492, 2024).
Hypertension (4 papers, 2020 to 2024). The presence of chronic increased pressure in the systemic arterial system. "A few genes were upregulated with hypertension (rather than genotype), including some that mapped to GO terms associated with positive regulation of the cytoskeleton (e.g., Nox4 and Alox15)." (PMID 38425784, 2024). "In summary, our study preliminarily showed that hypertension induces intracellular PUFAs to bind to phospholipids under the catalysis of ACSL4 and LPCAT3 to form PL–PUFAs, which are further oxidized by ALOX15, resulting in the accumulation of lipid peroxides." (PMID 39595632, 2024). "In support of this, ALOX15-deficient mice treated with wild-type peritoneal macrophages, which are a major source of ALOX15 in mice, lost their resistance toward L-NAME-induced hypertension." (PMID 36675152, 2023). "Studies of 15-lipoxygenating LOX-isoforms (ALOX15, ALOX15B) indicate that their regulation of vascular tone plays an important role in the development of hypertension." (PMID 36675152, 2023).
Insulin resistance (4 papers, 2018 to 2025). Increased resistance towards insulin, that is, diminished effectiveness of insulin in reducing blood glucose levels. "The upregulated Alox15 in the adipose impaired insulin signaling, but the whole-body and adipose-specific deficiency of Alox15 attenuated hyperglycemia and insulin resistance in mice." (PMID 31579613, 2019). "Indeed, this study proposes that an overexpression of ALOX15 stimulates the production of pro-inflammatory mediators, which promote insulin resistance induced through a high fat diet." (PMID 30282920, 2018).
ischemic stroke (4 papers, 2022 to 2025). A stroke disorder caused by obstruction of blood flow to the brain, due to thrombotic (local blood clot formation) or embolic (due to a blood clot or other material traveling from another site) event. "In conclusion, our results indicate that Cyn possesses neuroprotective properties against ischemic stroke by targeting Alox15, suppressing microglial activation and polarization, downregulating NLRP3-inflammasome components, and mitigating ferroptosis." (PMID 40026597, 2024). "Several previous studies have revealed the injury-promoting effect of ALOX15 in ischemic stroke and periventricular leukomalacia." (PMID 35186185, 2022). "ALOX15-mediated cell death and neuroinflammation have been observed in many central nervous system (CNS) diseases, such as ischemic stroke, ICH, multiple sclerosis (MS), and traumatic brain injury (TBI)." (PMID 35186185, 2022).
lymphoma (4 papers, 2020 to 2025). A malignant (clonal) proliferation of B- lymphocytes or T- lymphocytes which involves the lymph nodes, bone marrow and/or extranodal sites. "We are currently trying to identify HETE-containing carnitines and HETE-containing CoA esters in ALOX15 expressing L1236 human lymphoma cells using ALOX15-deficient lymphoma cells as negative controls." (PMID 40683369, 2025). "To validate the macrophages-ALOX15 signaling mediated lymphomagenesis in vivo, we established two EL4-lymphoma models by either subcutaneous xenograft or peritoneal injection in 12/15-LOX knockout (12/15-LOX−/−) mice as well as wild-type (WT) controls." (PMID 36600310, 2023).
myocardial ischemia (4 papers, 2018 to 2025). A disorder of cardiac function caused by insufficient blood flow to the muscle tissue of the heart. "Taken together, these data provide suggest the in vivo relevance of a pivotal role for ALOX15-mediated phospholipid peroxidation in PUFA-mediated susceptibility to myocardial ischemia." (PMID 35970840, 2022). "Our study, for the first time, provides a causal link between PUFAs intake and myocardial ischemia damage mediated by ALOX15-induced phospholipid peroxidation." (PMID 35970840, 2022). "Notably, two of the donors also suffered from myocardial ischemia, indicating that the decrease in ALOX15 expression indeed was associated with heart failure and not myocardial ischemia in itself." (PMID 30138423, 2018).
osteoporosis (4 papers, 2011 to 2023). A condition of reduced bone mass, with decreased cortical thickness and a decrease in the number and size of the trabeculae of cancellous bone (but normal chemical composition), resulting in increased fracture incidence. "One example of successful translational genetics is the identification of the arachidonate lipoxygenase 15 (Alox15) gene encoding an enzyme that modifies polyunsaturated fatty acids, as a candidate for osteoporosis." (PMID 21818327, 2011). "The guanine allele therefore either reduces or increases osteoporosis risk depending on which stage of life one is considering; if we consider the actions of ALOX15 during different life stages to be different functions then this allele is a clear case of an antagonistically pleiotropy." (PMID 22151998, 2011). "Alox15-knockout mice had higher BMD than normal mice, and Alox15 inhibitors enhance the BMD and bone loss rate in a rat osteoporosis model." (PMID 35399624, 2022).
peritonitis (4 papers, 2009 to 2023). Inflammation of the peritoneum (tissue that lines the abdominal wall and covers most of the organs in the abdomen). "Subsequent analysis of Alox15-expressing resolution-phase macrophages isolated from models of resolving peritonitis and acute N-acetyl-p-aminophenol-induced liver injury indicated a heightened efferocytic capacity." (PMID 31333453, 2019). "An independent study of peritonitis also excluded an intrinsic role for Alox15 during the ingestion of ACs as resolution-phase macrophages from both wild-type and Alox15 knockout mice ingested equally high amounts of ACs." (PMID 31333453, 2019).
Stroke (4 papers, 2022 to 2024). Sudden impairment of blood flow to a part of the brain due to occlusion or rupture of an artery to the brain. "In contrast to the deleterious roles of Alox15 in atherogenesis and stroke, a tissue-protective role of the enzyme in chronic inflammation was suggested." (PMID 39596127, 2024). "Since mouse Alox15 does only form small amounts of 15-HpETE, it remains unclear whether this minor AA metabolite is formed in sufficient amounts to mediate the deleterious effects of Alox15 in this stroke model." (PMID 39596127, 2024).
type 1 diabetes (4 papers, 2014 to 2023). "Alox15 catalyzes the oxidation of polyunsaturated fatty acids, such as arachidonic acid, during the formation of inflammatory mediators and has been linked to the development of type 1 diabetes." (PMID 24465846, 2014). "Deletion of ALOX15 alters macrophage and islet function in nonobese diabetic ALOX15 (null) mice, leading to decreased mRNA and protein levels of proinflammatory cytokines and preventing the development of type 1 diabetes." (PMID 27594770, 2016).
adenoma (3 papers, 2008 to 2024). A neoplasm arising from the epithelium. "We also checked the distribution of ALOX15 by using IHC assay, and ALOX15 was mostly expressed in gland cells of para-carcinoma tissues, and was expressed in small amounts in adenoma cells." (PMID 32106859, 2020).
alcoholic liver diseases (3 papers, 2017 to 2025). A disorder caused by damage to the liver parenchyma due to alcohol consumption. "This study investigated the role of bioactive lipid metabolites in alcohol-induced liver damage and tested the potential of targeting arachidonate 15-lipoxygenase (ALOX15) in treating alcoholic liver disease (ALD)." (PMID 28827690, 2017).
coronary artery disease (3 papers, 2012 to 2018). "Accordingly, the arachidonate 15-lipoxygenase (ALOX15) enzyme has been intrinsically linked with 4HNE production, and resultant pathophysiology in various complex conditions such as coronary artery disease and multiple sclerosis." (PMID 30282920, 2018). "Sequence variation in the ALOX15 gene has been previously identified and associated with coronary artery disease but the biological mechanisms underlying these associations are unexplored." (PMID 22879973, 2012). "Taken together, our results are consistent with a role for ALOX15/15-HETE signaling in ischemic heart disease." (PMID 27552229, 2016). "ALOX15-mediated 15-HETE synthesis may therefore be of biological importance in ischemic heart disease." (PMID 27552229, 2016). "However, the role of ALOX15 in the pathogenesis of ischemic heart disease remains unknown." (PMID 27552229, 2016). "The increased expression of ALOX15 mRNA in ischemic heart disease is in agreement with our earlier results but we had not previously investigated ALOX15B or ALOX12 expression in ischemic heart tissue." (PMID 27552229, 2016). "We have previously shown that the enzyme arachidonate 15 lipoxygenase (ALOX15), which catalyzes the conversion of arachidonic acid to 15-hydroxy eicosatetraenoic acid (15-HETE), is highly expressed in ischemic heart tissue, but its role in the pathogenesis of ischemic heart disease is unclear." (PMID 27552229, 2016). "Thus, we propose that increased ALOX15 expression in heart tissue under ischemic conditions may lead to increased production of 15-HETE, and thus may contribute to the pathogenesis of ischemic heart disease." (PMID 27552229, 2016). "In this study, we showed that expression of ALOX15 (but not ALOX15B or ALOX12) and 15-HETE levels were substantially higher in myocardial tissue from patients undergoing heart surgery for ischemic heart disease compared with myocardial tissue from those undergoing AVR surgery." (PMID 27552229, 2016). "Here we investigated whether increased ALOX15 expression and 15-HETE production could potentially contribute to ischemic heart disease by analyzing 15-HETE concentrations in heart tissue and serum from patients with and without ischemic heart disease." (PMID 27552229, 2016).
COVID-19 (3 papers, 2021 to 2024). A disease caused by infection with severe acute respiratory syndrome coronavirus 2. "Regarding the lipoxygenase biosynthetic pathway, we did not detect changes in the levels of ALOX5 or 12 between the different severity groups, unlike ALOX15, which was repressed in all COVID-19 patients, regardless of their severity." (PMID 39916956, 2024).
leukemia (3 papers, 2018 to 2024). A malignant (clonal) hematologic disorder, involving hematopoietic stem cells and characterized by the presence of primitive or atypical myeloid or lymphoid cells in the bone marrow and the blood. "Here, leukemia increases lipoxygenases arachidonate 15-lipoxygenase (Alox15/15-LO (ALOX15) and ALOX5), which metabolize polyunsaturated fatty acids." (PMID 37569414, 2023). "Two different studies from the same group have recently shown the relevance of arachidonate 5-lipoxygenase (Alox5) and arachidonate 15-lipoxygenase (Alox15) genes for the survival of CML leukaemia stem cells (LSC)." (PMID 29940987, 2018).
melanoma (3 papers, 2021). A malignant, usually aggressive tumor composed of atypical, neoplastic melanocytes. "Inhibition of ALOX15 contributes to abrogation of lipid peroxides accumulation; thus, ferroptosis resistant melanoma cells efficiently activate NRF2 to elevate the level of AKR1C3 and lead to a negative regulation of ALOX15." (PMID 34284753, 2021).
prostatic intraepithelial neoplasia (3 papers, 2012 to 2024). "Research by Kelavkar and his team revealed that epigenetic alterations—specifically hypermethylation of the ALOX15 promoter—amplify prostatic intraepithelial neoplasia." (PMID 38612771, 2024). "Epigenetic modification through hypermethylation of ALOX15 promoter increases prostatic intraepithelial neoplasia." (PMID 38612771, 2024). "One of the methylated CpG dinucleotides in the ALOX15 promoter was correlated with microdissected high‐grade prostatic intraepithelial neoplasia, PCa and metastatic human prostate tissues indicating ALOX15 was a valuable marker for disease initiation and progression." (PMID 37378426, 2023).
retinal degeneration (3 papers, 2022 to 2024). Degeneration of the retina. "ALOX15 expression declined between p21 and p49, when peak retinal degeneration occurred and plateaued between p49 and p60." (PMID 38396985, 2024).
subarachnoid hemorrhage (3 papers, 2022 to 2025). A serious neurological disorder characterized by intracranial hemorrhage into the subarachnoid space. "Other studies have shown that after subarachnoid hemorrhage, the sensitivity of endothelial cells and M2 cells to ferroptosis is enhanced by up‐regulating ALOX15, which destroys the blood–brain barrier, aggravates central inflammation, and further damages neurons." (PMID 40501108, 2025). "Our study was designed to determine the expression patterns and role of 15-lipoxygenase-1 (ALOX15) in subarachnoid hemorrhage (SAH) and to investigate whether cepharanthine (CEP) can inhibit ferroptosis by inhibiting ALOX15 in specific cell types." (PMID 35186185, 2022). "Cepharanthine inhibits RSL3-induced ferroptosis in endothelial cells and attenuate brain injury after subarachnoid hemorrhage (SAH), presumably through downregulation of ALOX15 which is a positive regulator of ferroptosis." (PMID 36435804, 2022).
acute coronary syndrome (2 papers, 2022). Signs and symptoms related to acute ischemia of the myocardium secondary to coronary artery disease. "This allows ENST00000538705.1 and ALOX15 to be considered as potential molecular targets for acute coronary syndrome therapy." (PMID 36011386, 2022). "In addition, circulating ENST00000538705.1 has been found to facilitate the progression of acute coronary syndrome through modulation of ALOX15." (PMID 36011386, 2022).
allergic asthma (2 papers, 2023). A asthma with a basis in a pathological type I hypersensitivity reaction. "We performed integrative analysis of three bulk gene expression profiles and identified five common IMR DEGs in childhood allergic asthma, including C3 and ALOX15, which are implicated in allergic asthma pathogenesis." (PMID 37123407, 2023). "Among them, SLC39A8, ALOX15, and CA2 showed higher expression, while SLC40A1 and C3 exhibited lower expression in patients with allergic asthma." (PMID 37123407, 2023).
atopic dermatitis (2 papers, 2024 to 2025). "The ALOX15 metabolic pathway regulates macrophages to promote anti-inflammatory mediator synthesis, and ALOX15 inhibition contributes to alleviating inflammatory cell infiltration during contact and atopic dermatitis." (PMID 39358326, 2024).
bacterial sepsis (2 papers, 2021 to 2023). "For example, ALOX15 and FCER1A were monocyte-associated genes, which have been found to play a pivotal role in the pathogenesis of bacterial sepsis." (PMID 34977060, 2021). "Recent research has demonstrated that ALOX15 and FCER1A are crucial to the pathogenesis of bacterial sepsis." (PMID 36823620, 2023).
breast tumor (2 papers, 2021 to 2022). "High ALOX15 mRNA levels were identified in metastatic breast tumor-derived epithelial-like MCF7 cells." (PMID 36010555, 2022).
diabetic nephropathy (2 papers, 2021 to 2023). "Regarding the association of ALOX15 with renal disease, proteinuria is decreased in Alox15−/− mice under glomerular injury by a streptozotocin-induced diabetic nephropathy model." (PMID 33595729, 2021).
diabetic retinopathy (2 papers, 2024). "Also, overexpression of ALOX15 and its metabolites (12-HETE and 15-HETE) has been implicated in diabetic retinopathy." (PMID 39436697, 2024).
eosinophilia (2 papers, 2025). "IL-4, IL-5, IL-13, ALOX15, CST1, POSTN, and CCL26 were significantly elevated in patients who had eosinophilia higher than 5%, but not IFN-γ." (PMID 40978168, 2025). "The results revealed that unlike IFN-γ, IL-4, IL-5, IL-13, ALOX15, CST1, POSTN, and CCL26 were significantly elevated in patients with eosinophilia greater than 5%." (PMID 40978168, 2025).
gastric tumor (2 papers, 2020 to 2023). "miR-522 overexpression in CAFs was associated with cisplatin/paclitaxel resistance of gastric tumor through activation of ubiquitin-specific protease 7 (USP7)/hnRNPA1 axis, inhibiting arachidonate lipoxygenase 15 (ALOX15) and ultimately decreasing chemosensitivity." (PMID 36671802, 2023).
heart failure (2 papers, 2018 to 2021). Inability of the heart to pump blood at an adequate rate to meet tissue metabolic requirements. "Another possible explanation is that ALOX15 expression patterns depend on the etiology of heart failure." (PMID 30138423, 2018). "Due to the possible therapeutic applications, the role of fibroblasts and ALOX15/B signaling in heart failure should be subject for further studies." (PMID 30138423, 2018). "ALOX15/B signaling may play an important role in heart disease, including heart failure." (PMID 30138423, 2018). "In the present study, we demonstrate for the first time that ALOX15 and ALOX15B is expressed in failing human hearts, and that ALOX15/B signaling therefore may contribute to human heart failure." (PMID 30138423, 2018). "The exact roles of ALOX15 and 15-HETE in the pathogenesis of heart failure are however unknown." (PMID 30138423, 2018). "Whether cardiac fibroblasts contribute to heart failure or other cardiac pathologies through ALOX15/B signaling has however not been described." (PMID 30138423, 2018).
helminth infection (2 papers, 2019 to 2025). "Interestingly, an increase in expression of Alox15 was observed to be associated with helminth infection and expression was increased further in the context of coinfection with P. aeruginosa." (PMID 31673002, 2019). "The results from qRT-PCR analysis revealed that gut-restricted helminth infection resulted in increased expression of Alox15 in lung tissue when compared with naive mice." (PMID 31673002, 2019). "Whereas a shift in 12/15-LOX oxylipin production in mice fed a high ω-6:ω-3 ratio diet is likely due to the availability of substrate for the metabolic enzyme and saturation of enzymatic activity, these increases were likely mediated by increased Alox15 expression following helminth infection." (PMID 40490052, 2025). "Interestingly, helminth coinfection induced a significantly greater level of Alox15 expression in lung tissue when compared with either P. aeruginosa infection alone or helminth infection alone." (PMID 31673002, 2019). "Although helminth infection further increased the production of 12/15-LOX oxylipins and increased expression of Alox15, responsible for producing these metabolites, inhibition of cyclooxygenase-dependent prostaglandin production with aspirin prevented helminth-exacerbation of disease." (PMID 40490052, 2025).